NRG1 (neuregulin 1)
Diseases named in the same sentence as NRG1 in open-access papers (continued):
Sharing a sentence is not in itself a finding about the gene and the disease.
dementia (5 papers, 2020 to 2024). Loss of intellectual abilities interfering with an individual's social and occupational functions. "Concordantly, our data showed reduced NRG1 mRNA levels in buffy coat samples obtained from patients diagnosed with various types of dementia." (PMID 35008438, 2021). "Plasma NRG1 differentiated AD MCI patients from neurological controls with an area under the curve of 88.3%, and AD dementia patients from NC with an area under the curve of 87.3%." (PMID 35606871, 2022). "Plasma NRG1 showed good performance in differentiating AD patients from NC both at MCI stage (AUC = 88.3%, 95% CI: 77.2–0.99.6%) and at dementia stage (AUC = 87.6%, 95% CI: 76.9–98.2%)." (PMID 35606871, 2022). "Plasma NRG1 concentration was higher in AD-MCI and AD dementia patients compared with neurological controls (respectively P = 0.005 and P < 0.001)." (PMID 35606871, 2022). "Our results showed that CSF NRG1 concentrations are enhanced in AD and MCI-AD as compared to controls and other dementias." (PMID 32690068, 2020). "Our results showed that CSF NRG1 levels are increased in AD and MCI-AD as compared to controls and other dementias." (PMID 32690068, 2020). "Research found that ADs and MCI-ADs had higher CSF NRG-1 than controls and non-AD dementias, and the CSF NRG-1 was correlated with cognitive evolution." (PMID 38659704, 2024). "Plasma NRG1 also displayed increased levels in non-AD dementia compared to NC and its accuracy in identifying AD at the dementia stage was moderate." (PMID 35606871, 2022). "Levels of NRG1 were significantly increased in the CSF of AD (+ 36%) and MCI-AD (+ 28%) patients compared to neurological controls and also non-AD MCI and non-AD dementias." (PMID 32690068, 2020). "The goal of this study was to assess CSF NRG1 levels and BACE1 concentrations in AD, MCI-AD, non-AD MCI, other dementias, and neurological controls and to compare these results with usual CSF AD CSF and synaptic biomarkers and cognition in the same groups." (PMID 32690068, 2020).
dilated cardiomyopathy (5 papers, 2012 to 2023). Cardiomyopathy which is characterized by dilation and contractile dysfunction of the left and right ventricles. "Following the identification of the gene deletion of the NRG-1 or ErbB receptors as the cause of dilated cardiomyopathy or cardiac malformation, research was conducted to explore the impact of NRG-1 on cardiac cell and tissue responses." (PMID 37895912, 2023). "After the observation that gene deletion of NRG-1 or ErbB receptors resulted in cardiac malformation or dilated cardiomyopathy, cardiac cell and tissue responses to NRG-1 have been studied." (PMID 23202898, 2012). "Ventricular muscle with the inactivation of ErbB4 may lead to severe dilated cardiomyopathy, and knockout of NRG-1 worsen the ventricular function post-Dox-induced cardiac injury." (PMID 30224945, 2018). "Because disruption of NRG1/ErbB signaling leads to dilated cardiomyopathy, an imbalance in the EC (NRG1)-CM (ErbB2/4) signaling may contribute to DCM." (PMID 25206341, 2014).
fibrosis (5 papers, 2016 to 2025). the formation of excess fibrous connective tissue in an organ or tissue in a reparative or reactive process. "An existing study reported that NRG1 exerts an inhibitory role in several fibrosis diseases including renal fibrosis." (PMID 34869303, 2021).
Hypertension (5 papers, 2019 to 2025). The presence of chronic increased pressure in the systemic arterial system. "Administration of neuregulin-1 (rhNRG-1) in STZ-induced diabetic rats reduced cell apoptosis and fibrosis as well as ameliorated hypertension." (PMID 33805825, 2021).
neuroblastoma (5 papers, 2014 to 2025). Neuroblastoma (NB) is the most common solid, extracranial childhood tumor. "The expression of NTRK1 in neuroblastoma cells stimulates the proliferation and migration of Schwann cells by inducing the secretion of neuregulin 1 (NRG1)." (PMID 41189817, 2025). "Using luciferase reporter assay, we tested the function of NRG1 rs2439302 in the human neuroblastoma cell line SHSY-5Y over expression CTCF." (PMID 37484916, 2023). "Here we show that NRG-1 stimulates synthesis of the two bioactive Cbl species adenosylcobalamin (AdoCbl) and methylcobalamin (MeCbl) in human neuroblastoma cells by both promoting conversion of inactive to active Cbl species and increasing neuronal Cbl uptake." (PMID 27057274, 2016). "Using the SH-SY5Y human neuroblastoma cell line, we examined the influence of NRG-1 on levels of six individual Cbl species, including the two bioactive Cbls, and the possible involvement of GSH." (PMID 27057274, 2016). "Media conditioned by NTRK1-expressing neuroblastoma cells induced SC proliferation and migration, while antibody-based NRG1 neutralization significantly decreased these effects." (PMID 25361003, 2014). "Our study provides strong evidence that NTRK1-expressing neuroblastoma cells both attract and stimulate the proliferation of adjacent Schwann cells by secreting NRG1, which in turn leads to NGF-mediated differentiation of neuroblastic cells." (PMID 25361003, 2014). "Here we demonstrate that NRG1 is also a predominant effector molecule of NTRK1-expressing neuroblastoma cells regulating communication with Schwann cells." (PMID 25361003, 2014). "NRG1 expression was restricted to cell lysates of NTRK1-positive neuroblastoma cells." (PMID 25361003, 2014). "In addition, the expression of several genes associated with growth suppression, including CDKN1A, EGR1, NRG1 and SEL1L, were also enhanced in all S(+)-ibuprofen-treated neuroblastoma cell lines." (PMID 24173829, 2014). "NRG1, expressed and secreted by NTRK1-positive SY5Y neuroblastoma cells, was identified as a chemokine and a major mediator of mitogenic effects in Schwann cells." (PMID 25361003, 2014). "Since NRG1 has previously been demonstrated to also be essential for Schwann cell migration, we next examined the impact of NTRK1-expressing neuroblastoma cells on the migratory activity of Schwann cells." (PMID 25361003, 2014). "Reanalysis of microarray data from human SY5Y neuroblastoma cells stably transfected with either NTRK1 or NTRK2 revealed upregulation of the mRNA for the SC growth factor, NRG1, in NTRK1-positive cells." (PMID 25361003, 2014). "Reanalyses of data from exon resolution mRNA arrays previously obtained from 101 primary neuroblastomas demonstrated a highly significant positive correlation between NTRK1 and NRG1 expression in vivo." (PMID 25361003, 2014). "Paracrine communication within this complex tumor are certainly not limited to the NRG1 and NGF effector molecules with the NTRK1 receptor, since the immune system and angiogenic tumor supply also contribute to overall neuroblastoma clinical presentation and aggressiveness." (PMID 25361003, 2014). "Taken together, these data show that NTRK1 expression causes upregulation and secretion of the Schwann cell-stimulating factor, NRG1, in vitro and is strongly correlated with NRG1 expression in vivo, suggesting a potential role for NTRK1 in the tumor-stroma dialog in neuroblastoma." (PMID 25361003, 2014). "In addition, S(+)-ibuprofen enhanced the expression of some favorable neuroblastoma genes (EPHB6, CD44) and genes involved in growth suppression and differentiation (EGR1, EPHA2, NRG1 and SEL1L)." (PMID 24173829, 2014). "Mutual interaction of NTRK1-expressing neuroblastomas with Schwann cells via the NRG1/NGF-axis helps to explain both the high Schwann cell infiltration in NTRK1-positive primary neuroblastomas and the absence of Schwann cells in NTRK1-negative neuroblastomas." (PMID 25361003, 2014).
neuroblastoma (continued). "According to our proposed model of bidirectional interaction, this might explain the diminished content of vital glia within the mixed-cell xenografts, since the Schwann cell effector molecule, NRG1, is not secreted by NTRK1-negative neuroblastoma cells." (PMID 25361003, 2014).
neuropathy (5 papers, 2016 to 2022). A disorder affecting the nervous system that manifests with pain, tingling, numbness, and/or muscle weakness. "A reduction in mTORC1 activity may also underlie the proposed beneficial effect of inhibiting neuregulin‐1 (NRG1) type III signaling in similar neuropathy models, although the role of NRG1 signaling in neuropathies is complex." (PMID 29210103, 2018). "Moreover, lapatinib prevented the TOCP-induced neuropathy through attenuating the activation of neuregulin 1/ErbB signaling." (PMID 29740279, 2018). "We hypothesized that modulation of Nrg1 levels and/or secretase activity may constitute a unifying treatment strategy for CMT neuropathies with focal hypermyelination as it could restore normal levels of myelination." (PMID 27799291, 2016).
bladder cancers (4 papers, 2011 to 2025). "In conclusion, our results suggest that NRG1–ERBB receptor interactions may have a significant role in the pathogenesis of bladder cancer and are potential targets for therapy." (PMID 21364580, 2011). "NRG1 gene fusions have been identified as oncogenic drivers in various solid tumors, including CRC, gallbladder, pancreatic, and bladder cancers." (PMID 38706895, 2024). "The objectives of this study were to determine expression of the two major isoforms of NRG1 and the ERBB family of receptors in human bladder cancer cell lines and tumour tissues." (PMID 21364580, 2011). "There is a wide spectrum of NRG1 and ERBB receptor expression in bladder cancer." (PMID 21364580, 2011).
brain injury (4 papers, 2014 to 2025). Acute and chronic (see also brain INJURIES, CHRONIC) injuries to the brain, including the cerebral hemispheres, CEREBELLUM, and brain STEM. "With an aim to investigate whether EC suppressing inflammatory aging and alleviating post-CA/CPR brain injury is associated with the inhibition of the NRG1-NF-κB pathway, we established a model of naturally aged 21-month-old rats subjected to CA/CPR." (PMID 41150741, 2025). "Neuregulin (NRG) complexes, NRG1/2/3/4, play important roles in many neurological disorders such as brain trauma, spinal cord injury, and SCZ." (PMID 35501678, 2022). "Since CM-associated brain injuries and AIS share similar pathophysiological features, we hypothesized that NRG-1 will reduce or prevent neuroinflammation and brain damage as well as improve survival in mice with late-stage experimental cerebral malaria (ECM)." (PMID 24433482, 2014).
breast tumour (4 papers, 2005 to 2021). "Collectively, these results underline the relevance of NRG1 as a heterogeneous factor expressed by CAFs in luminal breast tumours." (PMID 33692466, 2021). "As we had observed that NRG1 is highly expressed in the stromal compartment of breast tumour tissue, we next aimed to determine if CAFs are a source of NRG1." (PMID 33692466, 2021). "This indicates that the stromal cells are the major contributors of NRG1 expression in breast tumour tissue and suggests that activation of the HER3 pathway in tumour cells preferentially happens in a paracrine manner." (PMID 33692466, 2021). "Neuregulin 1 (NRG1) was described for the first time in 1992 as a 44-kD glycoprotein purified from the medium of a human breast tumor cell line." (PMID 33228092, 2020). "Correlations between HER-receptors and NRG1 in normal and breast tumour tissue among postmenopausal women." (PMID 23991224, 2013). "However, in comparison to other cancer entities, the expression of NRG1 in breast tumour cells is usually low and the gene is frequently silenced by DNA methylation." (PMID 33692466, 2021).
coronary heart disease (4 papers, 2008 to 2024). "Moreover, genes enriched in this pathway were related to an increased risk of coronary heart disease, such as NRG1, EGR2, and NOS1." (PMID 36032780, 2022).
cystic fibrosis (4 papers, 2015 to 2024). Autosomal recessive disorder caused by pathogenic variants in the CFTR gene (cystic fibrosis transmembrane conductance regulator), which encodes a chloride and bicarbonate channel expressed in epithelial cells, and follow the diagnosis criteria. "Similar approaches have led to the identification of heterozygous variants in the ROB1 and NRG1 transcription factors that govern filamentation and biofilm formation in strains recovered from cystic fibrosis patients." (PMID 39012122, 2024). "This suggests that the filamentation phenotype emerged independently within individual patients, and that the loss of function of NRG1 is a common mechanism of adaptation to the cystic fibrosis lung environment." (PMID 26588216, 2015). "Different homozygous nrg1 null mutations were identified between isolates, indicating that loss of NRG1 occurred independently in different patients and is a common adaptation to the lung environment in individuals with cystic fibrosis." (PMID 31892130, 2019). "Yet another possibility is that loss of function of NRG1 may confer niche-specific fitness advantages, consistent with the observed heterogeneity in bacterial populations that has been attributed to spatial and temporal heterogeneity in the cystic fibrosis lung environment." (PMID 26588216, 2015).
esophageal squamous cell carcinoma (4 papers, 2017 to 2025). Esophageal squamous cell carcinoma (ESCC) is a type of esophageal carcinoma (EC) that can affect any part of the esophagus, but is usually located in the upper or middle third. "In sharp contrast, elevated expression of NRG1 was observed in esophageal squamous cell carcinoma, and this was associated with poor disease outcome." (PMID 41439026, 2025).
multiple sclerosis (4 papers, 2011 to 2025). A progressive autoimmune disorder affecting the central nervous system resulting in demyelination. "Earlier studies showed loss of NRG1 expression in multiple sclerosis-active lesions." (PMID 40277942, 2025). "In addition to the findings presented here for AD, NRG1 signaling has been shown to be pathogenic in models of chronic pain, multiple sclerosis, and ALS." (PMID 37903620, 2023). "NRG1 levels reduced in multiple sclerosis, and exogenous NRG1 reduced the disease progression in animal models." (PMID 40277942, 2025). "The EGF-like domain of NRG1 was shown to suppress experimental autoimmune encephalomyelitis (EAE), an animal model of multiple sclerosis." (PMID 40277942, 2025).
neurofibroma (4 papers, 2012 to 2021). An intraneural or extraneural neoplasm arising from nerve tissues and neural sheaths. "Strikingly, overexpression of neuregulin-1 by itself (Nf1 wild type) is sufficient to induce neurofibroma formation followed by MPNST development, although at low frequency." (PMID 34445326, 2021). "Based on the notion that the Schwann cell growth factor neuregulin-1 and its receptor EGFR are expressed in neurofibroma and MPNST, mice models overexpressing neuregulin-1 or EGFR were developed." (PMID 34445326, 2021).
schwannoma (4 papers, 2013 to 2023). A benign, usually encapsulated slow growing tumor composed of Schwann cells. "In human schwannomas, ErbB2 and Nrg1 expression was found to be similarly changed compared to sural nerve biopsies from healthy human individuals." (PMID 27236462, 2016). "However, cells within schwannomas do not retain axonal contact and must adapt to the loss of axonally provided Nrg1." (PMID 36944680, 2023). "Transcriptomic alterations, such as the neuregulin 1 (NRG1)/ErbB2 pathway, have been described in schwannomas." (PMID 23354516, 2013). "Our results concur with earlier array analysis data on schwannomas, such as caveolin-1 (CAV1) downregulation, as well as with other studies conducted, using techniques such as qRT-PCR [i.e., neuregulin 1 (NRG1)-ErbB2-ErbB3 upregulation] and immunohistochemistry analysis (CCND1 upregulation)." (PMID 23354516, 2013). "Our studies suggest that pS6 may be a specific biomarker of Nrg1 but not TGFα production in schwannoma." (PMID 36944680, 2023).
Sepsis (4 papers, 2023 to 2024). Sepsis is defined as life-threatening organ dysfunction caused by a dysregulated host response to infection. "(2022] showed that the dosage of NGR1 in mice (30 mg/kg/d) and epithelial cells (4 μM) can reduce the mitochondrial fission in allergic rhinitis, the same dose was chosen by us to explore the effects of NRG1 on the mitochondria of endothelial cells under sepsis." (PMID 38389274, 2024). "Notably, neuromodulin-1 (NRG-1), adenosine, and Chinese yam can reduce the inflammatory response, protect cardiomyocytes, and ameliorate sepsis-induced cardiac dysfunction by inhibiting RAAS overactivation." (PMID 36593471, 2023). "Other studies have demonstrated that exogenous NRG1 administration attenuates oxidative stress and inflammation by inhibiting the production of reactive oxygen species IL-1β and NLRP3 inflammasome, and supports cardiac repair, sepsis, traumatic spinal cord injury." (PMID 39312480, 2024).
triple-negative breast carcinoma (4 papers, 2022 to 2025). An invasive breast carcinoma which is negative for expression of estrogen receptor (ER), progesterone receptor (PR), and human epidermal growth factor receptor 2 (HER2). "NRG1 regulates metastasis of triple-negative breast cancer cells via c-myc ubiquitination." (PMID 40959099, 2025). "Besides, the NRG1/HER3/HER2 axis is reported to trigger anchorage-independent growth of basal-like/triple-negative breast cancer cells." (PMID 36765036, 2023). "In that study, activation of the NRG1/HER3/HER2 axis induced anchorage-independent growth of basal-like/triple-negative breast cancer cells, without affecting cell proliferation." (PMID 36765036, 2023). "In vitro analyses unveiled that the activation of the NRG1/ERBB3/ERBB2 axis robustly induces anchorage-independent growth of basal-like/triple-negative breast cancer cellular models, without significant effects on cell proliferation, differentiation, and migration in adhesion." (PMID 35406375, 2022).
autoimmune disease (3 papers, 2024 to 2025). A disorder resulting from loss of function or tissue destruction of an organ or multiple organs, arising from humoral or cellular immune responses of the individual to their own tissue constituents. "While the research on NRG1 and ANAX3 in autoimmune diseases is limited, our findings have identified them as IBD-feature genes linked to disulfidptosis." (PMID 38433839, 2024).
brain infarct (3 papers, 2019 to 2021). "It is possible that subjects with SCA who had silent cerebral infarctions may account for those with higher NRG-1, BDNF or PDGF-AA levels." (PMID 35935682, 2021). "The finding that the highly conserved Nrg1-ICD has a neuroprotective role may foster the identification of new therapeutic targets to treat neurodegeneration following brain infarct." (PMID 31583038, 2019).
diverticulosis (3 papers, 2015 to 2019). "As diverticular disease (DD) is associated with intestinal hypoganglionosis, the NRG1-ErbB2/ErbB3 system and the nAChR were studied in patients with DD and controls." (PMID 31920561, 2019). "Further studies are required to unravel whether a deficiency of the NRG1/ErbB2/ErbB3 system observed in DD may also occur in asymptomatic diverticulosis." (PMID 31920561, 2019).
esophageal cancer (3 papers, 2024 to 2025). A primary or metastatic malignant neoplasm involving the esophagus.
head and neck cancer (3 papers, 2017 to 2025). A primary or metastatic malignant neoplasm affecting the head and neck. "Some preclinical data suggest that expression of the ligand neuregulin-1 is associated with HER3 activation in ovarian and head and neck cancer." (PMID 28881753, 2017).